EED (embryonic ectoderm development)
Description:
Polycomb group (PcG) protein. Component of the PRC2/EED-EZH2 complex, which methylates 'Lys-9' and 'Lys-27' of histone H3, leading to transcriptional repression of the affected target gene. Also recognizes 'Lys-26' trimethylated histone H1 with the effect of inhibiting PRC2 complex methyltransferase activity on nucleosomal histone H3 'Lys-27', whereas H3 'Lys-27' recognition has the opposite effect, enabling the propagation of this repressive mark. The PRC2/EED-EZH2 complex may also serve as a recruiting platform for DNA methyltransferases, thereby linking two epigenetic repression systems. Genes repressed by the PRC2/EED-EZH2 complex include HOXC8, HOXA9, MYT1 and CDKN2A.
Synonyms: hEED; WAIT-1; COGIS; WAIT1
Tractability: Small molecule: a structure with a bound ligand is known; a high-quality ligand is known; it has a binding pocket of medium quality. PROTAC: it is named in the literature on targeted protein degradation; ubiquitination databases record sites on it; its protein half-life has been measured; a small molecule that binds it is known.
Chemical probes: A-395 (high quality), EED226 (high quality), UNC6852 (high quality)
Gene: Protein-coding gene on chromosome 11 (86,201,212 to 86,279,807, forward strand). Ensembl gene ENSG00000074266.
Subcellular location: Nucleus; Chromosome
Subcellular location (Human Protein Atlas): Nucleoplasm; Cytosol
Pathways (Reactome):
Disease: Defective pyroptosis; HCMV Early Events
Gene expression (Transcription): PRC2 methylates histones and DNA; Transcriptional Regulation by E2F6
Cell-Cell communication: Negative Regulation of CDH1 Gene Transcription
Cellular responses to stimuli: Oxidative Stress Induced Senescence
Chromatin organization: PKMTs methylate histone lysines
Developmental Biology: Activation of anterior HOX genes in hindbrain development during early embryogenesis
Immune System: Regulation of PD-L1(CD274) transcription
Signal Transduction: Regulation of PTEN gene transcription
Gene Ontology:
Molecular function: enzyme activator activity; identical protein binding; protein binding; transcription corepressor binding; nucleosome binding; chromatin binding; promoter-specific chromatin binding
Biological process: heterochromatin formation; negative regulation of DNA-templated transcription; negative regulation of transcription by RNA polymerase II; facultative heterochromatin formation; spinal cord development
Cellular component: ESC/E(Z) complex; nucleoplasm; nucleus; chromatin silencing complex; chromosome; pronucleus; sex chromatin
Genetic constraint (gnomAD): Loss-of-function variants: 8 observed, 35.19 expected, observed/expected ratio (o/e) 0.23, 90% interval 0.13 to 0.41. The upper end of that interval is the gene's LOEUF score, 0.41, which puts it in group 1 of 6, group 1 being the genes least tolerant of losing a copy. Missense variants: 256 observed, 420.29 expected, observed/expected ratio (o/e) 0.61, 90% interval 0.55 to 0.68. Synonymous variants: 156 observed, 134.9 expected, observed/expected ratio (o/e) 1.16, 90% interval 1.01 to 1.32.
Gene-disease validity (ClinGen):
ClinGen rates the evidence that EED causes each of these diseases.
Cohen-Gibson syndrome (autosomal dominant): Moderate.
Homologues: Orthologues: chimpanzee EED (100% identical), dog EED (100% identical), macaque EED (100% identical), mouse Eed (100% identical), pig EED (100% identical), rat Eed (100% identical), rabbit EED (99% identical), guinea pig EED (94% identical), tropical clawed frog eed (93% identical), zebrafish eed (90% identical), Drosophila melanogaster escl (54% identical), Drosophila melanogaster esc (49% identical), and 1 more.
Diseases named in the same sentence as EED in open-access papers:
EED is named in the same sentence as 110 diseases in open-access papers, as found by Europe PMC text mining. Sharing a sentence is not in itself a finding about the gene and the disease. The quoted sentences say what the papers report.
Weaver syndrome (15 papers, 2018 to 2025). Weaver syndrome (WVS) is a rare, multisystem disorder characterized by tall stature, a typical facial appearance (hypertelorism, retrognathia) and variable intellectual disability. "Clinically, EED mutations are associated with cancer and Cohen–Gibson and Weaver syndromes, both characterized by skeletal abnormalities and intellectual disability." (PMID 40417780, 2025). "Cohen-Gibson syndrome (COGIS) was described later, involving mutations in EED (Embryonic Ectoderm Development), and can be distinguished from Weaver syndrome by more prevalent cryptorchidism, cervical spine abnormalities, and cardiac abnormalities." (PMID 38448973, 2024). "De novo germline mutations in the human EED gene lead to Weaver syndrome, a disease characterized by skeletal defects, advanced bone age and overgrowth." (PMID 36727213, 2023). "Similar to EZH2, several mutations in EED have also been identified in patients with Weaver syndrome, while mutations in SUZ12 have been associated with a Weaver-like syndrome presenting with macrocephaly, postnatal overgrowth, and skeletal abnormalities." (PMID 36845425, 2023). "Partial mutations in genes encoding the EZH2 or EED subunits lead to Weaver syndrome, characterized by variable intellectual disability and distinctive facial features." (PMID 36727213, 2023). "Interestingly, germline de novo mutations in either EED or EZH2 result in Weaver syndrome, characterised by growth and congenital defects and cognitive deficit in affected humans." (PMID 30236109, 2018). "The rare Weaver syndrome linked to developmental cognitive deficits is caused by autosomal dominant mutations in any one of the three PRC2 core components EZH2, EED and SUZ12." (PMID 37842084, 2023). "Weaver syndrome (MIM #277590) is an autosomal dominant condition caused by germline monoallelic mutations affecting the genes encoding the core PRC2 subunits, EZH2, EED and SUZ12." (PMID 31575610, 2019). "In humans, heterozygous mutations in the EZH2, EED and SUZ12 genes cause congenital overgrowth, often marked by features that are typical of those observed in Weaver syndrome." (PMID 31575610, 2019). "Significantly, de novo germline mutations in EED or EZH2 in humans lead to Cohen-Gibson and Weaver syndromes, characterised by overgrowth, skeletal defects and learning/cognitive disabilities." (PMID 30005706, 2018). "In humans, de novo germline mutations in EZH2 lead to Weaver Syndrome (OMIM 28229590) and de novo germline mutations in EED lead to Cohen-Gibson syndrome, both of which are characterised by overgrowth." (PMID 30005706, 2018). "Likewise, two of three reported Weaver syndrome-associated mutations in SUZ12 are nonsynonymous substitutions within its VEFS domain, a key functional domain for its association with EZH2 and EED, which, when deleted, abolishes the enzymatic activity of PRC2." (PMID 31575610, 2019). "Germline heterozygous mutations in the genes encoding core PRC2 members (EZH2, EED and SUZ12), NSD1 and DNMT3A have been implicated in a triad of highly phenotypically related human developmental disorders: Weaver syndrome, Sotos syndrome and Tatton-Brown–Rahman syndrome, respectively." (PMID 31575610, 2019). "Notably, JARID2 exhibited the highest overlap with CHARGE (~7%, CHD7), BAFopathy (~4%, including ARID1A, ARID1B, SMARCB1, SMARCA2, SMARCA4), and the PCR2 complex, which houses Cohen–Gibson syndrome (COGIS) and Weaver syndrome (WVS) (~4%, EED, EZH2)." (PMID 37762546, 2023). "In this study, partial loss of EED function in the paternal germline was sufficient to mediate significant, though relatively subtle changes in epigenetic and transcriptional regulation in paternal offspring, but not the spectrum of phenotypic characteristics observed in Weaver syndrome patients." (PMID 30236109, 2018).
breast carcinoma (12 papers, 2013 to 2025). "The elevated expression of PRC2 components, except EED, was confirmed in breast cancers compared to normal tissues." (PMID 41413688, 2025). "DZNep(3- Deazaneplanocin), a compound that disrupts the PRC2, effectively depletes EZH2, Suz12, and EED and inhibits H3K27me3 in breast cancer and AML cells." (PMID 23985559, 2013). "DZNep (3-deazaneplanocin A hydrochloride) is a S-adenosylhomocysteine hydrolase (SAAH) inhibitor depleting cellular levels of PRC2 components (EZH2, SUZ12, and EED), suppressing histone methylation, and inducing selective apoptosis in BC cell lines and primary mammary tumors." (PMID 40141248, 2025). "A significant correlation with poor prognosis was also observed for high EZH2 and SUZ12 expression in sarcoma and in lung adenocarcinoma; for EZH2 in breast cancer; for EZH2 and EED expression in ovarian cancer." (PMID 34202528, 2021). "We have identified three highly connected modules, EED, DHX9, and AURKA, which are extremely activated in TNBC tumors compared to both normal tissues and other breast cancer subtypes." (PMID 31134131, 2019). "In a study using the EZH2 inhibitor 3-deazaneplanocin A (DZNep), it was found that its treatment depleted breast carcinoma cells of the PRC2 complex members (EZH2, SUZ12, and EED),and subsequently reactivated expression of IGFBP-3." (PMID 28042859, 2016).
malignant peripheral nerve sheath tumor (11 papers, 2018 to 2024). Malignant peripheral nerve sheath tumor (MPNST) is a rare and often aggressive soft tissue sarcoma occurring in a wide range of anatomical sites. "Recent studies reported that mutations of SUZ12 and EED had occurred in malignant peripheral nerve sheath tumors as well as head and neck high-grade malignant peripheral nerve sheath tumors had led to the loss of trimethylation at lysine 27 of histone H3 (H3K27me3), a downstream gene of EZH231,32." (PMID 30120321, 2018). "The SUZ12 and EED genes also feature LOF mutations in T-ALL and are particularly frequent in Malignant Peripheral Nerve Sheath tumours (MPNST)." (PMID 36105358, 2022). "Patients with microdeletions in the NF1 gene were reported to have a 4-fold increased risk of malignant peripheral nerve sheath tumors (MPNST) and this risk was further increased with codeletion of SUZ12 or EED gene." (PMID 39257551, 2024). "For example, in malignant peripheral nerve sheath tumor, PRC2 is recurrently inactivated through component EED or SUZ12 but not EZH2, despite a complete loss of H3K27me3." (PMID 36612203, 2022). "In conjunction with additional tumor suppressors, the PRC2 subunits EED and SUZ12 (but not EZH2) are mutated in 85% of malignant peripheral nerve sheath tumors (MPNST) that develop in patients with NF1 mutations." (PMID 34617019, 2021).
leukemia (7 papers, 2015 to 2022). A malignant (clonal) hematologic disorder, involving hematopoietic stem cells and characterized by the presence of primitive or atypical myeloid or lymphoid cells in the bone marrow and the blood. "In MLL-rearranged leukemia, PRC2 promotes acute leukemogenesis through repression of general senescence regulators, and disruption of EED or both EZH paralogs inhibits growth of these leukemias." (PMID 34617019, 2021). "Interestingly, shRNA-mediated inhibition of PRC2 subunit EED, SUZ12, or EZH1/EZH2 causes leukemia cells to stop proliferation and differentiation." (PMID 32436117, 2020). "To analyze whether PICOT colocalizes with nuclear EED in leukemia cells, we performed immunofluorescence staining of PICOT and EED in four different human leukemia cell lines." (PMID 31527584, 2019). "EED directly interacts with EZH2, therefore Orkin and colleagues developed peptides that selectively disrupt the EED/EZH2 interaction, thereby reducing EZH2 protein levels as well as H3K27me3 in MLL-AF9-mediated leukemia." (PMID 36105358, 2022). "For example, UNC1999 and SAH-EZH2 peptide (binds EED, resulting in dissociation of EZH1–EED and EZH2–EED complexes) showed activity against MLL leukemia." (PMID 34298959, 2021).
lymphoma (7 papers, 2020 to 2024). A malignant (clonal) proliferation of B- lymphocytes or T- lymphocytes which involves the lymph nodes, bone marrow and/or extranodal sites. "Individual examination of the EZH2, SUZ12, and EED genes showed that CRPC and prostate neuroendocrine carcinoma demonstrated an association with frequent alterations in each of the PRC2 encoding genes, while in GCB-DLBCL lymphoma a high correlation was found only with alterations in the EZH2 gene." (PMID 34202528, 2021). "EED226 was one of the first EED inhibitors reported and was found to specifically inhibit H3K27 methylation, either in lymphoma cells harboring WT-EZH2 or EZH2 mutants." (PMID 36076977, 2022). "This suggests that GOF mutations in the SET domain of EZH2 can augment the sensitivity of lymphoma cells to the inhibition of either EZH2, SUZ12, or EED." (PMID 34202528, 2021). "Additionally, EED and SUZ12 are upregulated in multiple cancers, including lymphoma, breast cancer, head, and neck squamous cell carcinoma (NHSCC), and colorectal cancer." (PMID 36076977, 2022). "Interestingly, the expression of PRC2 components EZH2, EED, and SUZ12 was lower in CD19+ normal B-cells as compared to that in lymphoma cell lines." (PMID 32850364, 2020). "Interestingly, although EED226 failed to enter clinical trials, another EED inhibitor, MAK683, developed on the basis of this scaffold, is currently in phase 2 clinical trials for the treatment of lymphoma." (PMID 36076977, 2022).
neuroblastoma (7 papers, 2019 to 2024). Neuroblastoma (NB) is the most common solid, extracranial childhood tumor. "For example, the EED gene that encodes a critical component of polycomb-repressive complex 2 that plays a critical step in neuroblastoma growth showed exon 8 and 9 skipping after RBM39 depletion." (PMID 34788094, 2021). "PI3Kα inhibitor PIK-75 (78.9% cytotoxicity) stimulates anti-neuroblastoma activity by destabilizing MYCN and sensitizing tumor cells to anthracyclines, and indeed increased cytotoxicity with PIK-75 was associated with PPM1D and GNA13 gain, and DNMT3A, CBL, EED and ASXL2 loss." (PMID 34722256, 2021). "Supporting a conserved function for PRC2 in MHC-I silencing, EED KO restored cell surface expression of MHC-I in human SCLC and neuroblastoma cells." (PMID 31564637, 2019). "In the case of neuroblastoma, tumors with high amplification of MYCN show hyperactivation of PRC2-associated components such as EZH2, EED, and RBBP7 with respect to non-MYCN-amplified neuroblastoma cases." (PMID 31920530, 2019).
Cohen-Gibson syndrome (6 papers, 2018 to 2025). "To date, 15 human missense mutations in EED have been reported as pathogenic for Cohen-Gibson syndrome." (PMID 41329158, 2025).
diffuse large B-cell lymphoma (4 papers, 2020 to 2024). "UNC7700 exhibited a strong degradation activity against EED (DC50 = 111 nM; Dmax = 84%) and EZH2WT/EZH2Y641N (DC50 = 275 nM; Dmax = 86%) in a diffuse large B-cell lymphoma DB cell line." (PMID 38389844, 2024). "It selectively degraded EED (Dmax = 95%), EZH2 (Dmax = 95%), and SUZ12 (Dmax = 80%), and it was observed that the proliferation of both the EZH2 mutant diffuse large B-cell lymphoma (DLBCL) cell line and the EZH2 wild-type (WT) rhabdoid cancer cell line was effectively suppressed." (PMID 38389844, 2024).
glioma (4 papers, 2012 to 2021). A benign or malignant brain and spinal cord tumor that arises from glial cells (astrocytes, oligodendrocytes, ependymal cells). "In renal papillary cell carcinoma, low-grade glioma and hepatocellular carcinoma, poor prognosis was significantly correlated with high expression of all three genes, EZH2, SUZ12, and EED." (PMID 34202528, 2021). "The occupancy of the methylation-related histones (H3K4me2, H3K27me3, H3K9me3 and H4K20me3) on the LMO3 promoter was detected after the inhibition of EZH2, EED and DNMT3A in glioma cells." (PMID 25829251, 2015). "PHF19 could form the PRC2 with Ezh2, EED, and SUZ12, knockdown of the PHF19 gene suppressed Ezh2 phosphorylation and proliferation in glioma cells." (PMID 35003347, 2021). "Surprisingly, p27, p21, p16, FBXO32, EED, Cyclin E and TGF-β-1 were not induced in EZH2 knockdown cells further suggesting that EZH2 influences the motile phenotype of glioma cells independent of histone methylation." (PMID 23077658, 2012).
hepatocellular carcinoma (4 papers, 2010 to 2023). A malignant tumor that arises from hepatocytes. "For instance, EZH2 and EED are direct targets of the tumor suppressor miR-101 in hepatocellular carcinoma (HCC) cells." (PMID 37345170, 2023). "Our study also provided first experimental evidence to show that induction of endogenous miR-101 indeed is accompanied with lower EZH2, EED and SUZ12 level and histone 3 lysine 27 trimethylation in human hepatoma cells." (PMID 20444294, 2010). "In hepatocellular carcinoma, PRC2 complex epigenetically repressed miR-101 in a c-Myc-mediated manner, which in turn inhibited the expression of two subunits of PRC2 (EZH2 and EED), thus creating a double-negative feedback loop that regulates the process of carcinogenesis." (PMID 27385092, 2016).
Intellectual disability (4 papers, 2021 to 2025). "Cohen-Gibson syndrome (COGIS, OMIM #617561) is an overgrowth disorder characterized by dysmorphic facial features, advanced bone age, skeletal abnormalities, associated with variable intellectual disability, and caused by de novo mutations in EED." (PMID 34831364, 2021). "Mutations in the genes encoding other components of PRC2, namely EZH2 and EED, also lead to overgrowth, macrocephaly, advanced bone age, variable intellectual disability and distinctive facial features." (PMID 34681033, 2021). "For example, variants in PRC2 members EED, SUZ12 and EZH2 share a similar DNAm signature, and a similar clinical spectrum characterised by overgrowth and intellectual disability." (PMID 39843918, 2025).
multiple myeloma (4 papers, 2018 to 2022). "Using Affymetrix microarrays, we analyzed the expression of PRC2 core genes EZH2, SUZ12, and EED in normal bone marrow plasma cells (BMPCs, n = 5), primary myeloma cells from patients (MMCs, n = 206), and human myeloma cell lines (HMCLs, n = 26)." (PMID 30285865, 2018). "Investigating the survival prognosis in multiple myeloma (MM) patients, we have shown that PRC2 core genes, EZH2, SUZ12 and EED, were significantly overexpressed in MM cells compared to normal plasma cells, making these cells sensitive to EPZ-6438, an inhibitor of EZH2." (PMID 34202528, 2021). "Inhibitors targeting both EZH1 and EZH2 (EZH1/2 dual inhibitors) and EED (EED inhibitor) have also been developed, and these inhibitors show better tumor-eradicating effects than EZH2-specific inhibitors in the treatment of AML, multiple myeloma, and EZH2 inhibitor-resistant DLBCL cells." (PMID 33374737, 2020).
myelodysplastic syndrome (4 papers, 2016 to 2022). A clonal hematopoietic disorder characterized by dysplasia and ineffective hematopoiesis in one or more of the hematopoietic cell lines. "Mutations also occur outside the PRC2 catalytic domain: EED-I363M, which is a LOF mutation, has been identified in patients with myelodysplastic syndrome (MDS) and related diseases." (PMID 31024026, 2019).
neurofibroma (4 papers, 2020 to 2024). An intraneural or extraneural neoplasm arising from nerve tissues and neural sheaths. "To determine if PRC2 inactivation was sufficient for selumetinib resistance, we used CRISPR interference (CRISPRi) to suppress SUZ12 or EED in NF1-mutant NF95.11b neurofibroma cells." (PMID 38216572, 2024). "Whole exome sequencing identified recurrent somatic short variants (SSVs) in the core PRC2 components SUZ12 or EED in Group 1 but not Group 2 or Group 3 histological neurofibromas and MPNSTs." (PMID 38216572, 2024). "Hence, mutually exclusive bi-allelic loss-of-function mutations in the PRC2 core proteins SUZ12 and EED are recurrently observed in NF1-associated MPNSTs, while not observed in the pre-cancerous tumours, neurofibromas." (PMID 38448973, 2024).